IL10 (interleukin 10)
Diseases named in the same sentence as IL10 in open-access papers (continued):
Sharing a sentence is not in itself a finding about the gene and the disease.
colitis (continued). "The model therefore predicts that the function of the mucosal barrier will determine whether or not colitis develops in in specific sets of Il10−/− animals." (PMID 22848611, 2012). "A decrease in lymphoid cells was not restricted to Rag1−/− hosts because lymphoid cell production in the BM was also decreased in a lymphocyte-replete model of colitis in which WT mice infected with Helicobacter hepaticus develop intestinal inflammation in the absence of IL-10 signaling." (PMID 23200826, 2012). "However, NFAT has an important role in regulation of T cells, and since Il10−/− colitis model is driven by the innate and adaptive immune system, we cannot exclude inhibitory effects of VIVIT on T cells as an additional mechanism for amelioration of colitis." (PMID 22479554, 2012). "AOM/DSS-colitis, but not IL-10−/− mice, could provide a powerful murine model to mechanistically investigate CIN in colitis-associated carcinogenesis." (PMID 21799775, 2011). "IL-10-/- C57BL/6 mice usually do not develop colitis in pathogen-free conditions." (PMID 22176654, 2011). "This is consistent with our previous experiments, and suggests that, despite being crucial pro-inflammatory cytokine produced by macrophages, TNF-α could be either exhausted or downregulated by IL-10, cytokine inhibiting TNF-α production, at this stage of colitis." (PMID 22132181, 2011). "UCA reduced colonic levels of IFNγ in IL-10−/− mice but did not attenuate colitis." (PMID 21060867, 2010). "However, the lack of barrier dysfunction in the 30–35 wk old Il10−/− mice reported here correlates very well with the low incidence of spontaneous colitis (2 of 15 = 13%) that we observed in 36 wk old Il10−/− mice." (PMID 20808919, 2010). "Moreover, AOM-treated germ free Il10−/− mice failed to develop colitis and consequently colorectal tumors as confirmed by histological evaluation." (PMID 19551144, 2009). "Also, the gram-negative Bacteroides vulgatus bacterium fails to trigger significant inflammation in IL-10−/− mice whereas the same organism triggers severe colitis in HLA-B27/β2 microglobulin transgenic rats." (PMID 19841748, 2009). "As M. avium paratuberculosis is a mycobactin auxotroph and is not known to replicate outside a host, spontaneous colitis of IL-10-/- mice upon transfer to conventional housing is possibly the result of exposure to Mycobacterium species, which are commonly found in soil and water." (PMID 18533024, 2008). "In vivo studies using a DSS-induced colitis mouse model further demonstrated that HME-MUL-F2 could alleviate colitis symptoms, increase body weight and colon length, reduce pro-inflammatory cytokines (IL-1β, TNF-α, IL-6, MCP-1), and increase anti-inflammatory cytokines (IL-10)." (PMID 40283912, 2025). "Notably, neither Il10−/− nor Gsta4−/− mice developed colitis when housed in an SPF environment." (PMID 39819335, 2025). "Finally, although our group has previously demonstrated that healthy human fecal microbiota induces colitis when transplanted to GF Il-10−/− mice, the present study did not compare the relative ability of healthy vs IBD patient fecal microbiota to induce inflammation in Il-10−/− mice." (PMID 39113097, 2024). "Elucidating the exact upstream mechanism by which IL-10 restrains VLC ceramide accumulation may also aid in refining recombinant IL-10 therapies that have been tested in the clinic for colitis but ultimately failed to meet their endpoints due to lack of precision and efficacy." (PMID 39132450, 2024). "Interestingly, IL-10 KO GF mice on the other hand had a lack of colitis and immune activation." (PMID 37901813, 2023). "This study suggests that immunogenetically manipulated mice with deletion of IL-10 may have reduced capacity to contain MMTV infection in a mouse-strain-specific manner, and the antiviral inflammatory responses may contribute to the complexity of IBD with the development of colitis and dysbiosis." (PMID 36869359, 2023).
colitis (continued). "Moreover, adding Indigo Naturalis to DSS-induced colitis mice can promote the expression of IL-10 and IL-22 in colonic lamina propria lymphocytes but not in AHR-deficient mice, which may be related to reduced production of regulatory cytokines." (PMID 37179416, 2023). "However, treatment by a recombinant strain expressing IL-10 presented very limited protective effects in the in vivo colitis model, while the B. bifidum BGN4-SK treatment effectively enhanced antioxidant capability, protected colonic epithelial integrity and inhibited colonic inflammation." (PMID 35672695, 2022). "Furthermore, mice with lacking IL-10 and IL-10R are more likely to develop spontaneous colitis." (PMID 36437465, 2022). "Thus the gnotobiotic IL-10 knockout mice failed to develop the colitis and subsequent CAC." (PMID 34386004, 2021). "Our data also suggest changes in cytokine receptor gene expression on MulTreg, which may include a shift from IL-10 and IL-27 induced regulatory function towards enhanced TGFBR1 signaling which has been shown to induce Treg retention in inflamed sites and control of experimental colitis." (PMID 34539651, 2021). "Moreover, NGAL controls intestinal epithelial cell homeostasis as a result of its ability to impact on the gut microbiota: in an IL-10−/− murine experimental model of colitis, lack of NGAL resulted in expansion of facultative pathogenic strains, thus facilitating colitis onset." (PMID 34830212, 2021). "In addition to IL-10, Breg-derived transforming growth factor β1 (TGF-β1) and interleukin 35 (IL-35) also have been demonstrated to mediate the protective roles of Bregs against dextran sodium sulfate-colitis, experimental autoimmune encephalomyelitis, and experimental uveitis." (PMID 34302556, 2021). "Moreover, MSC-derived exosomes alleviate colitis in vivo by inhibiting expression of IL-7 and inducible nitric oxide synthase (iNOS) in mouse colonic macrophages, thus limiting the production of nitric oxide and the expression of TNF-α, IL-6 and IL-1β and increasing IL-10 secretion." (PMID 32365813, 2020). "Another study performed in mice model of experimental colitis has shown that treatment of colitic mice with EcN_OMVs could reduce intestinal inflammation by inhibiting the expression of IL-1β, TNF-α and IL-17 and enhancing the expression of IL-10 in colonic tissues." (PMID 32854612, 2020). "Interestingly, germ-free IL-10−/− mice do not develop colitis and the administration of antibiotics prevents colitis, indicating that the gut microbiota is necessary for the development of colitis." (PMID 32670290, 2020). "B. vulgatus induces colitis in HLA/B27-β2m rats, but does not induce inflammation in other colitis models (e.g., IL-10−/− or IL-2−/− mice), which makes it difficult to assess whether this bacterium has colitogenic activity in a complex community in IL-10−/− mice." (PMID 31281321, 2019). "BF could not prevent DSS-induced colitis in IL-10 knockout mice." (PMID 28683149, 2017). "Moreover, DSS-colitis was not ameliorated in IL-10 knockout mice with BF colonization." (PMID 28683149, 2017). "Thus, the effect of Lcn2 deficiency on cytokine production from macrophages could not be directly involved in the deteriorated colitis of Lcn2/IL-10 DKO mice." (PMID 27734904, 2016). "Our study herein provides molecular insights into how the IL-10/IL-10R signaling axis regulates NLRP3 inflammasome activation in macrophages during acute and chronic LPS/ATP stimulation, and helps to identify novel targets that could be exploited to treat colitis." (PMID 26412089, 2015). "Thus, theoretically, the lack of sOPN might lead to the amelioration of colitis in IL-10 KO mice by decreasing the production of pro-inflammatory cytokines from intestinal macrophages." (PMID 26274807, 2015). "Thus, the expanded cells ameliorated colitis without expressing an abundance of IL-10." (PMID 26024301, 2015).
colitis (continued). "However, discrepancy exists on the fact that adenovirus-based IL-10 systemic delivery might not be able to reduce established colitis." (PMID 25889561, 2015). "Thus the observed surge in IL-10 might derive from other cells in an effort to down-modulate the markedly pro-inflammatory local and systemic cytokine profile, which is usually observed in the chronic phase of DSS-induced colitis." (PMID 24873968, 2014). "Whether it be endotoxin challenge, bacterial infection, or colitis due to the absence of IL-10, compromised barrier function and entry of luminal material into the subepithelial compartment may activate resident submucosal cell types and result in exacerbated mucosal cytokine production." (PMID 24244444, 2013). "Twelve days following oral infection, C. jejuni could be detected in the ileum and colon (in 55.2% and 69.0% of infected mice, respectively), but not in the stomach or duodenum of IL-10−/− mice with colitis, whereas healthy wildtype control animals remained free of C. jejuni." (PMID 22563475, 2012). "Finally, due to the ability of cis-UCA to increase IL-10 secretion, coupled with our observation of a trend towards a cis-UCA-induced increase in FoxP3+IL-10+ T cells in the DSS studies, we next carried out a series of experiments in the IL-10−/− mouse model of colitis." (PMID 21060867, 2010). "In addition, specific cytokine may regulate inflammation in an organ-specific manner as it has been shown that Treg lacking the ability to produce IL-10 failed to inhibit skin inflammation and colitis." (PMID 19272184, 2009). "In the absence of STING, T cells contribute to the exacerbation of colitis, whereas Th1 cells pretreated with STING agonists ameliorate the severity of colitis via IL-10 mediation." (PMID 41041344, 2025). "In the absence of IL-10, the MMTV Sag-induced lymphocyte proliferation leads to disturbed gut homeostasis with microbial dysbiosis that in turn triggers colitis." (PMID 39817448, 2025). "In this model, the absence of IL-10 leads to increased production of IFN-γ and the development of spontaneous colitis." (PMID 41465474, 2025). "We supplemented 11-week-old IL-10−/− mice with or without IAA and observed that by the time the mice reached 16 weeks, the vehicle group developed significant spontaneous colitis, whereas the IAA group did not exhibit noticeable inflammation." (PMID 39068517, 2024). "Kidney was not affected by colitis; however, NAC despite increasing CAT, GSH, and GSH/GSSG ratio promoted lipid peroxidation (increased MDA) and pro-inflammatory action (decreased IL-10)." (PMID 37577725, 2023). "It did not affect the transcription of TNF, IL-6, and IL-10, suggesting that additional proinflammatory cues, as provided during DSS colitis, are required to induce TNF upregulation." (PMID 36413219, 2023). "In this report, we show that WIN 18,446 treatment also inhibits colitis in a more chronic model of IBD—Mdr1a−/− mice, but not in the Il10−/− mice." (PMID 37764666, 2023). "There is also prominent participation of Il10 and Tgfb1 in the immune networks of TNBS-colitis regardless of the trial and sex that counteracts the inflammatory imbalance." (PMID 37047397, 2023). "While no direct comparison of the development of colitis was performed between these models, the authors did report a significant increase in DAI at day 3, and did not observe in increase in IL-10 levels, which is consistent with what we now report." (PMID 37189092, 2023). "In general, IL-10 levels are not changed or even increased in patients with ulcerative colitis and the mice model of DSS-induced colitis through regulating the innate and adaptive immune response." (PMID 36176442, 2022). "As for anti-inflammatory cytokines, LCA, DCA, and HDCA did not alter the mRNA levels of Il10 while DCA and HDCA increased the mRNA levels of Il4 in colitis mice." (PMID 36050867, 2022).
colitis (continued). "In accordance with the higher colitis severity of this model, the numbers of IFN-γ+ and IFN-γ+ IL-17A+ CD4+ cells, but not IL-17+ or IL-10+ CD4+ T cells, in the large intestinal lamina propria were higher in LysoPS-treated mice than in control mice." (PMID 35608941, 2022). "In DSS induced colitis, however, which does not depend on T cells, GPR183 did not contribute to pathogenesis unless the mice were on the Il10-/- gene background." (PMID 36389671, 2022). "Il10−/− mice in our animal facility do not develop spontaneous colitis, and AIEC infection by itself only marginally induced colitis." (PMID 36094114, 2022). "The efficacy of ESM in IL-10−/− mice with spontaneous colitis has not yet been elucidated, thus we investigated the potential protective role of ESM on the effects of colitis and gut microbiota modulation in IL-10−/− female mice." (PMID 35662934, 2022). "The results showed that the mRNA expression levels of Cgas, Il10, Cxcl10, Ifnb1, Tnf, Il6, and Il1b exhibited no obvious difference between GCV and vehicle treatment groups in DSS-colitis in STINGgt/gt mice (all p > 0.05)." (PMID 36467059, 2022). "In contrast to the DSS model, during colitis in 12-week or 30-week old Il10−/−Il33Cit/+ mice, neither citrine+ cells nor CD45−CD90+ fibroblasts were increased compared to littermate Il10+/-Il33Cit/+ mice." (PMID 33953267, 2021). "Oral administration of NK210 and/or NK219 did not affect colitis-related colon shortening, myeloperoxidase activity, and TNF-α and IL-10 expression in the colon." (PMID 34667205, 2021). "While the IL-10 expression in DSS-induced colitis mice without treatment was lower than that in the normal mice and colitis mice treated with SSP or 5-ASA." (PMID 32714185, 2020). "After 7-days’ administration of SSP and 5-ASA, the numbers of CD4+CXCR5+IL-10+ (Tfh10) and CD4+CXCR5+Foxp3+ (Tfr) (E5) were dramatically increased when compared with those in colitis mice without treatment." (PMID 32581849, 2020). "Conditional knock out mice lacking Maf in all T cells developed spontaneous late-onset colitis, correlating with a decrease of FOXP3+RORγt+ T cells proportion, dampened IL-10 production in the colon and an increase of inflammatory TH17 cells." (PMID 30992496, 2019). "Using animal models of experimental colitis and arthritis it was shown that Gram-negative bacteria, possibly through the TLR2/IL-10 axis, reduced inflammation, whereas Gram-positive bacteria contributed to a more severe disease." (PMID 29503707, 2018). "Likewise, IL10−/− mice develop colitis-associated cancers that do not demonstrate the chromosomal instability that is typically encountered in most human IBD-CRCs; recent studies suggest the need for additional microbial and immunological stressors to improve IL10−/− mouse model fidelity." (PMID 30386335, 2018). "In the present study, the LC27 and LC67 mixture PM, synergistically rather than additively, attenuated TNBS-induced colitis such as colon shortening, myeloperoxidase activity, TNF-α and IL-10 expression, and Th17 and Treg cell differentiation." (PMID 29760423, 2018). "The injection of anti-IL-10 antibody did not affect the development of DSS-induced colitis in WT BMDM-transferred WT mice, suggesting that anti-IL-10 antibody has no profound pro-inflammatory effect." (PMID 28733636, 2017). "To assess the role of Lcn2 in intestinal inflammation, we compared intestinal inflammation between IL-10 KO and Lcn2/IL-10 DKO mice, because Lcn2 KO mice did not develop spontaneous colitis." (PMID 27734904, 2016). "The progress of colitis did not affect TGF-β secretion, but IL-10 production was markedly increased in KO mice (p < 0.001)." (PMID 27139220, 2016). "Sodium butyrate ameliorated histological colitis and decreased levels of tumor necrosis factor (TNF)-α and IL-6 in IL-10−/− mice compared with those without treatment." (PMID 27886121, 2016).
colitis (continued). "The levels of IFN-γ, TNF-γ, IL-1β, IL-12p70 and IL-6, but not IL-10, were significantly higher in IL-21RKO mice than those in C57BL/6 mice on day 5 after DSS-induced colitis (*P < 0.05)." (PMID 27545302, 2016). "The results show that MMF significantly inhibited mRNA expression of pro-inflammatory cytokines IFN-γ, TNF-α, IL-12, IL-6, and IL-1β in mice with TNBS-induced colitis; however, MMF did not inhibit the expression of IL-10 mRNA." (PMID 26561804, 2015). "IL-10 and IFN-γ, which showed no significant change in our experiments, were not elevated in acute and subacute stages of DSS-induced colitis." (PMID 24948848, 2014). "In contrast, the severity of H. hepaticus-induced colitis in mice lacking both IL-10 and IFN-γ was comparable to mice lacking IL-10 alone, indicating that IFN-γ does not favour colitis development." (PMID 24489792, 2014). "Oral B. breve administration ameliorated colitis in immunocompromised mice given naïve CD4+ T cells from wild-type mice, but not Il10−/− mice." (PMID 22693446, 2012). "Mice with colitis, regardless of diet, presented higher concentrations of all measured cytokines (TNF, IL-6, IL-4, IL-10, IFNy), and MCP-1/CCL2." (PMID 22073943, 2011). "Whereas most mast cell-sufficient Il10−/− mice did not develop colitis by 9 months of age (mean histologic score ± SEM = 13±2), most DKO mice developed at least moderate colitis (mean ± SEM histologic score = 27±4)." (PMID 20808919, 2010). "We observed increased IL-10 mRNA levels, concurrent with increased expression of forkhead box P3 (Foxp3) mRNA, the master regulatory gene for regulatory T cells, in splenic tissues from DSS-induced colitis mice administered with DCF0620 (data not shown)." (PMID 41567191, 2025). "In addition, the anti-inflammatory cytokines, IL-10 and IL-22, are also increased in DSS- induced colitis, suggesting that negative feedback is activated to limit the progress of inflammation." (PMID 35933374, 2022). "Additionally, tenascin-C protein has also been shown to be elevated in the colitic colons of Il-10−/− mice, a genetic model of IBD, suggesting this upregulation is not specific to the DSS colitis model." (PMID 35669358, 2022). "Furthermore, both DSS and GML pretreatment increased expression of colonic il10, indicating that the favorable effect of GML was not mediated directly via IL-10, which is crucial for preventing spontaneous colitis and maintaining homeostasis." (PMID 34634946, 2021). "However, Mix4 did not promote Il10 expression in colonic CD11b+ cells, although effectively ameliorating DSS-induced colitis." (PMID 32561763, 2020). "Although it could not directly detect the IL-10 protein, Il-10 mRNA expression, and high levels of FOXP3 protein in colitis tissues would support the hypothesis that TOE could induce Tregs." (PMID 33092149, 2020). "The suppressive effects of B cells in colitis have been demonstrated by TCR-α−/− × Igμ−/− mice lacking B cells spontaneously developing more severe colitis than TCR-α−/− mice and adoptive transfer of IL-10-producing CD1d+CD5+ Bregs inhibiting the DSS-induced intestinal injury in a mouse model." (PMID 29784012, 2018). "We confirmed that reactivation of colitis significantly increased colonic level of pro-inflammatory cytokines IL-6, IL-1β, and TNF- α and decreased level of colonic anti-inflammatory cytokine TGF-β, but IL-10 levels were not affected." (PMID 28871257, 2017). "It is interesting to note that recent experimental work using non-infectious models of colitis have indicated that IFN-γ drives expression of the IL-10R1 in colonic epithelium and that IFN-γ and IL-10 upregulate the target gene SOCS3 in intestinal epithelium, which can help control inflammation." (PMID 24942690, 2014). "However, our results indicate there are two differences: 1) Pam3CSK4-induced IL-10 production is abrogated in CCR8-/- PMφ but not with R243 treatment, and 2) suppression of TNBS colitis in CCR8-/- mice is not as evident as that in R243-treated mice." (PMID 24714157, 2014).